LATS2 (large tumor suppressor kinase 2)
Diseases named in the same sentence as LATS2 in open-access papers (continued):
Sharing a sentence is not in itself a finding about the gene and the disease.
bladder cancer (3 papers, 2018 to 2021). "Furthermore, GAS1 and LATS2 were negatively correlated with miR-942-3p in the TCGA database and bladder cancer cell lines at the mRNA and protein levels, respectively." (PMID 33499877, 2021). "As exemplified by the LATS2 and RND3 genes, vitamin C restored 5hmC levels in T24 cells; these levels were relatively low in bladder cancer cells compared with normal bladder cells, and 5mC showed an opposite trend." (PMID 30005692, 2018). "Since LATS2 inhibits the activity of TAZ in the Hippo signaling pathway, we speculated that TAZ and miR-942-3p might form a positive feedback loop in bladder cancer." (PMID 33499877, 2021).
cardiac hypertrophy (3 papers, 2019 to 2022). "We found that haploinsufficiency of Lats2 attenuates both cardiac dysfunction and hypertrophy in response to pressure overload." (PMID 34873220, 2021). "It should be noted, however, that cardiac specific overexpression of dominant negative Lats2 enhanced cardiac hypertrophy and inhibited cardiomyocyte apoptosis in response to TAC9." (PMID 34873220, 2021). "Taken together, these results suggest that pressure overload-induced cardiac hypertrophy, LV dysfunction and heart failure were significantly alleviated in Lats2 +/- mice compared to in NTG mice." (PMID 34873220, 2021). "Cardiomyocyte-specific overexpression of a dominant-negative form of Lats2 notably increased ventricular hypertrophy and suppressed TAC-induced cardiomyocyte apoptosis." (PMID 31632964, 2019). "Thus, the goals in this study were to examine the effects of a loss of Lats2 function, using systemic Lats2 heterozygous KO (Lats2 +/-) mice, and investigate the role of endogenous Lats2 in cardiac hypertrophy and heart failure during pressure overload." (PMID 34873220, 2021). "Cardiac hypertrophy and dysfunction induced by 4 weeks of TAC were attenuated in Lats2 +/- mice, and interstitial fibrosis and apoptosis were suppressed." (PMID 34873220, 2021). "Although the effect upon cardiomyocyte apoptosis was reproduced here, we did not observe the enhancement of cardiac hypertrophy in Lats2 +/- mice in response to TAC." (PMID 34873220, 2021). "Lats2 is also a negative regulator of cardiac hypertrophy, where its overexpression did not affect cardiomyocyte apoptosis but rather reduced cardiomyocyte size." (PMID 31632964, 2019). "Since we and others have shown that the roles of the Hippo pathway components are cell-type dependent, it is likely that the lack of enhancement of cardiac hypertrophy in Lats2 +/- mice in response to TAC is attributable to the effect of Lats2 downregulation in non-myocytes." (PMID 34873220, 2021).
cholangiocarcinoma (3 papers, 2015 to 2025). A carcinoma that arises from the intrahepatic biliary tree (intrahepatic cholangiocarcinoma) or from the junction, or adjacent to the junction, of the right and left hepatic ducts (hilar cholangiocarcinoma). "In human cholangiocarcinoma cells, G9a and H3K9me2 levels are increased at the promoter region of the LATS2 gene, which promotes its repression, while G9a knockdown increases LATS2 expression and reduces YAP nuclear localization." (PMID 40661662, 2025). "Recently, Ma and co-workers presented evidence that the histone-lysine methyltransferase EHMT2 is up-regulated in human cholangiocarcinoma, which enhances cell growth and invasiveness by epigenetically silencing the Hippo pathway kinase large tumor suppressor 2 (LATS2)." (PMID 34344448, 2021). "Interestingly, in human cholangiocarcinoma cells, G9a suppresses LATS2 expression levels." (PMID 40661662, 2025).
esophageal cancer (3 papers, 2012 to 2017). A primary or metastatic malignant neoplasm involving the esophagus. "Loss of function of either LATS1 or LATS2 leads to a variety of tumor types including soft tissue sarcomas, leukemia, as well as breast, prostate, lung and esophageal cancers, which suggests they function as tumor suppressors in tumor pathogenesis." (PMID 22909338, 2012). "Frequent loss of heterozygosity of LATS2 has been reported in esophageal cancer." (PMID 29145896, 2017). "Furthermore, miR-373 affected the esophageal cancer cells growth through inhibition of LATS2 expression." (PMID 29145896, 2017).
renal fibrosis (3 papers, 2021 to 2024). A final common manifestation of a wide variety of chronic kidney diseases characterized by glomerulosclerosis and tubulointerstitial fibrosis. "Since maladaptive repair after IRI contributes to the gradual aggravation of renal fibrosis, we examined the influence of proximal tubule-specific Lats2 ablation on renal fibrosis after AKI." (PMID 37894939, 2023). "In agreement with these previous studies, our findings also confirmed a significantly increased p-TAZ, p-YAP, and LATS2 in renal fibrosis mice, following inhibition of miR-4709-3p." (PMID 34931960, 2021). "The results indicated a significantly increased p-TAZ and LATS2 in the renal fibrosis-positive compared to the control." (PMID 34931960, 2021). "The Western blot assay confirmed a significantly elevated p-TAZ, p-YAP, and LATS2 in renal fibrosis samples transfected with miR-4709-3p-inhibitors compared to the sham group." (PMID 34931960, 2021). "Overall, the study concludes that aberrant miR-4709-3p expression plays an essential function in the renal fibrosis progression, and miR-4709-3p overexpression could advance obstructive renal fibrosis via LATS2 targeting in Hippo signaling pathway." (PMID 34931960, 2021). "The present investigation hypothesized that miR-4709-3p suppresses obstructive renal fibrosis via Hippo signaling by targeting Large Tumor Suppressor Kinase 2 (LATS2)." (PMID 34931960, 2021). "Luciferase assay miR-4709-3p modulates renal fibrosis by targeting LATS2." (PMID 34931960, 2021).
B-cell lymphoma (2 papers, 2021 to 2022). "In this study in B-cell lymphomas, we also found the low mutation frequencies of the major components of Hippo pathway like LATS1 (1%), LATS2 (1%), YAP1 (1%), and FAT1 (6%)." (PMID 34926267, 2021).
breast tumor (2 papers, 2013 to 2018). "To further elucidate the means by which LATS2 might exert its breast tumor suppressive activity, we performed RNA sequencing (RNA-seq) analysis of WT- and Lats2-CKO PyMT tumors." (PMID 30456386, 2018).
cognitive deficits (2 papers, 2024 to 2025). "For instance, Lats2, a core component of the hippocampus signaling pathway, is considered to be highly correlated with cognitive deficits." (PMID 38421132, 2024). "To determine how inhibition of Hippo signaling might affect AD‐related cognitive impairments and pathology, we generated 5xFAD mice with conditional KO of Lats1 and Lats2 in forebrain neurons." (PMID 40923675, 2025).
fatty liver (2 papers, 2019 to 2022). "Conversely, LATS2 inhibits hepatic cholesterol accumulation in the liver, explaining the increase in fatty liver incidence in LATS2-deficient mice." (PMID 35907883, 2022).
fibrosis (2 papers, 2022 to 2024). the formation of excess fibrous connective tissue in an organ or tissue in a reparative or reactive process. "However, how LATS2 is degraded and whether this degradation is related to YAP activation and LN fibrosis have not been reported." (PMID 38459604, 2024).
Fulminant hepatic failure (2 papers, 2020 to 2024). Hepatic failure refers to the inability of the liver to perform its normal synthetic and metabolic functions, which can result in coagulopathy and alteration in the mental status of a previously healthy individual. "Similarly, EZH2 can be enriched in the LATS2 promoter region to affect its expression through H3K27me3 in fulminant hepatic failure." (PMID 38652219, 2024). "Importantly, evidence supports that EZH2 can be recruited into the promoter of LATS2 to augment H3K27me3 methylation, thus restraining LATS2 expression in fulminant hepatic failure." (PMID 38652219, 2024).
head and neck carcinoma (2 papers, 2014 to 2023). A carcinoma that arises from the head and neck region. "Finally, to verify our observations, we analysed the expression of LATS2 and its correlation with OSCC histological grade in patients using the TCGA Head and Neck Cancer dataset." (PMID 37553362, 2023).
Hyperglycemia (2 papers, 2021 to 2025). An increased concentration of glucose in the blood. "Functional assays further demonstrated that knockdown of YAP1 via shRNA (sh‐YAP1), in contrast to MST1 (sh‐MST1) or LATS2 (sh‐LATS2) knockdown, significantly alleviated hyperglycemia‐induced cardiomyocyte damage and the induction of ferroptosis." (PMID 40279648, 2025).
Obesity (2 papers, 2022 to 2024). Accumulation of substantial excess body fat. "Within NASH-HCC, the junction protein JCAD linked to obesity interacts with LATS2, hindering its kinase activity by binding to the kinase domain but not affecting the connection between LATS2 and MOB1." (PMID 38933330, 2024). "Lats1 and Lats2 mRNA were upregulated in both obesity models." (PMID 36229481, 2022).
parathyroid adenomas (2 papers, 2019 to 2021). "The reduced LATS2 levels detected in parathyroid adenomas are in agreement with the inhibitory effect on LATS2 expression levels exerted by miR-372, which has been found to be overexpressed in a subset of parathyroid adenomas and most parathyroid cancers." (PMID 33670622, 2021).
pulmonary fibrosis (2 papers, 2015 to 2019). Chronic progressive interstitial lung disorder characterized by the replacement of the lung tissue by connective tissue, leading to progressive dyspnea, respiratory failure, or right heart failure. "Finally, we found that Lats2-underexpressing BMSCs inhibited early pulmonary fibrosis in ALI lung tissue." (PMID 31772503, 2019). "Finally, Lats2-underexpressing BMSCs alleviated lung injury and early pulmonary fibrosis." (PMID 31772503, 2019).
renal carcinoma (2 papers, 2020 to 2024). A carcinoma arising from the epithelium of the renal parenchyma or the renal pelvis. "LATS2 plays important roles in kidney development and renal cancer." (PMID 38459604, 2024). "In renal cancer, lncRNA HOTTIP recruits both EZH2 and LSD1 to the promoter region of LATS2 and represses LATS2 transcription by increasing H3K27me3." (PMID 33050646, 2020).
adenoma (1 paper, 2018). A neoplasm arising from the epithelium. "Interestingly, the transcription pattern of the Lats2-CKO PyMT adenoma/MIN displayed remarkable resemblance to that of the WT-PyMT carcinoma, suggesting that deletion of Lats2 facilitates a carcinoma-like gene expression pattern even at early stages of tumorigenesis." (PMID 30456386, 2018).
adenosquamous carcinoma (1 paper, 2018). A carcinoma composed of malignant glandular cells and malignant squamous cells. "Surprisingly, a notable portion of Lats1-CKO PyMT mice developed adenosquamous carcinoma, a tumor type not observed in Lats2-CKO PyMT mice." (PMID 30456386, 2018).
Anxiety (1 paper, 2018). Intense feelings of nervousness, tension, or panic often arise in response to interpersonal stresses. "Evidence of an eQTL effect was predicted for a lead SNP in LATS2, a positive regulator of histone methyltransferase activity a process important in anxiety-related behaviours." (PMID 30571770, 2018).
autoimmune disease (1 paper, 2024). A disorder resulting from loss of function or tissue destruction of an organ or multiple organs, arising from humoral or cellular immune responses of the individual to their own tissue constituents. "Thus, our data extend the current knowledge of LATS2 to the field of autoimmune disease, providing evidence that LATS2 is a promising therapeutic target in LN progression." (PMID 38459604, 2024).
brain tumor (1 paper, 2016). "Indeed, further analysis of glioblastoma multiforme (GBM), the most common and most aggressive malignant primary brain tumor, supports the possibility of LATS2 for tumorigenesis through PRC2." (PMID 27434182, 2016).
breast metaplastic carcinoma (1 paper, 2018). "Notably, LATS1, but not LATS2, was down-regulated in human breast metaplastic carcinoma, which is thought to occur via transdifferentiation of a subpopulation of cancer cells." (PMID 30456386, 2018).
Chronic colitis (1 paper, 2021). A chronic inflammatory disease of the large intestine (colon, cecum and rectum). "Among the 479 archived tissue blocks, 56.32% of adjacent non-tumor tissues had high LATS2 expression, compared with only 23.08% of chronic colitis tissues, 15.91% of low-grade intraepithelial neoplasia tissues, 9.09% high-grade intraepithelial neoplasia tissues, and 33.80% of cancerous tissues." (PMID 34699318, 2021).
chronic kidney disease (1 paper, 2023). Impairment of the renal function secondary to chronic kidney damage persisting for three or more months. "How LATS2, the upstream factor in the Hippo signaling pathway, functions in acute and chronic kidney diseases remains poorly understood." (PMID 37894939, 2023).
cognitive decline (1 paper, 2025). "The mice were subjected to a battery of behavioral tests at 5 months and 9 months of age to assess the effects of neuronal KO of Lats1 and Lats2 on AD‐associated cognitive decline." (PMID 40923675, 2025). "Our results indicated that 5xFAD mice with ablation of Lats1 and Lats2 were protected against cognitive decline compared with control 5xFAD mice, and this protection was correlated with a marked reduction in neurodegeneration." (PMID 40923675, 2025). "The observation that downstream Hippo signaling inhibition by KO of Lats1 and Lats2 helped to prevent cognitive decline and reduce neurodegeneration in 5xFAD mice prompted us to investigate how KO of Lats1 and Lats2 may be beneficial for the survival of neurons." (PMID 40923675, 2025).
colon adenocarcinoma (1 paper, 2020). "We characterized YAP/TAZ expressions in colon adenocarcinoma (COAD) and identified a new regulator of their expressions by finding out that miR-429 modulated YAP/TAZ expression via targeting LATS2." (PMID 33414893, 2020).
embryonic carcinoma (1 paper, 2025).
esophageal tumors (1 paper, 2011). "In testicular and esophageal tumors, in which they are abundant, miR-372 and miR-373 have been reported to act as oncogenes repressing LATS2, a serine-threonine kinase involved in cell cycle regulation." (PMID 22027184, 2011).
gastric adenocarcinoma (1 paper, 2020). "Recent studies have shown that miR-107 regulates proliferation and invasion of gastric adenocarcinoma cells by regulation of LATS2." (PMID 32106857, 2020).
heart failure (1 paper, 2021). Inability of the heart to pump blood at an adequate rate to meet tissue metabolic requirements. "Further investigation regarding the underlying mechanism for the cardioprotection afforded by Lats2 inhibition may allow the development of effective and selective interventions to treat heart failure." (PMID 34873220, 2021). "TAC-induced increases in LV dysfunction and heart failure are alleviated in Lats2 +/- mice, accompanied by decreases in apoptosis and fibrosis." (PMID 34873220, 2021). "This warrants further investigation to evaluate the effect of Lats2 suppression upon heart failure progression, using large animal models." (PMID 34873220, 2021). "We speculate that systemic and 50% inhibition of Lats2 during pressure overload should delay the development of heart failure." (PMID 34873220, 2021). "Thus, interventions to inhibit Lats2 may be useful for delaying the development of heart failure in patients with pressure overload." (PMID 34873220, 2021).
hepatoblastoma (1 paper, 2024). Hepatoblastoma (HB) is a malignant hepatic tumor and is the most common pediatric liver cancer. "Reduced LATS2 expression promotes hepatoblastoma progression by inhibiting ferroptosis through the YAP1/ATF4/PSAT1 axis." (PMID 39247829, 2024). "The role of LATS2, a core component of the Hippo pathway cascade, in ferroptosis initiation in hepatoblastoma (HB) has not yet been investigated." (PMID 39247829, 2024).
human papillomavirus infection (1 paper, 2022). "On the other hand, KEGG investigation revealed that LATS2 was associated with human papillomavirus infection and ECM–receptor interaction." (PMID 36118851, 2022).
intrahepatic cholangiocarcinoma (1 paper, 2021). A carcinoma that arises from the intrahepatic bile duct epithelium in any site of the intrahepatic biliary tree. "Previously, we have shown that activation of Lats2 in Akt/NRas murine liver tumors resulted in delayed hepatocarcinogenesis and the elimination of intrahepatic cholangiocarcinoma (ICC)-like lesions in the liver." (PMID 33232824, 2021).
ischemia (1 paper, 2023). A hypoperfusion of the BLOOD through an organ or tissue caused by a PATHOLOGIC CONSTRICTION or obstruction of its BLOOD VESSELS, or an absence of BLOOD CIRCULATION. "In this study, we utilized a conditional knockout mouse strain in which Lats2 was specifically ablated in proximal tubular cells to explore the role of LATS2 in a model of maladaptive kidney repair after severe kidney injury (unilateral ischemia/reperfusion injury [U-IRI])." (PMID 37894939, 2023).
lentivirus infection (1 paper, 2020). Virus diseases caused by the Lentivirus genus. "First, we overexpressed or blocked lncRNA NEAT1/LATS2 by lentivirus infection." (PMID 32157157, 2020).
liver fibrosis (1 paper, 2024). "It was recently reported that LATS2 might be involved in liver fibrosis, which is consistent with our results." (PMID 38459604, 2024).
lupus (1 paper, 2024). "In this study, we examined YAP activation and LATS2 downregulation in LN kidney biopsy samples (LN: n = 8, normal: n = 2) and lupus-prone MRL/lpr mice (n = 8 for each disease stage)." (PMID 38459604, 2024). "First, LATS2-KO mice on an MRL/lpr background were not used in this study due to the difficulty of establishing a lupus model." (PMID 38459604, 2024).
lupus nephritis (1 paper, 2024). Glomerulonephritis in the context of systemic lupus erythematosus. "Interestingly, the expression of LATS2 but not LATS1 was significantly downregulated in lupus nephritis specimens, especially in proximal tubules." (PMID 38459604, 2024).
malignant pleural mesothelioma (1 paper, 2019). A malignant neoplasm that arises from mesothelial cells in the pleura and shows a diffuse growth pattern. "LATS2 mutations were also found in 11% of malignant pleural mesotheliomas and, of particular interest, co-occurring mutations of NF2 and LATS2 correlated with poor prognosis." (PMID 31450674, 2019).
meningioma (1 paper, 2020). A generally slow growing tumor attached to the dura mater. "Whilst LATS2 remained elevated in response to MLN3651 treatment, pYAP expression was only enhanced in some meningioma (3/6), suggesting an efficient feedback pathway that inhibits YAP phosphorylation." (PMID 32629964, 2020). "In meningioma, combination of MLN3651 and selumetinib inhibited Raf/MEK/ERK activation induced by MLN3651, whilst maintaining CRL4-DCAF1 inhibition through increased LATS2." (PMID 32629964, 2020).
metastatic tumors (1 paper, 2024). "LATS2 expression has been shown to be lower in CRC tissue compared to adjacent tissue and even lower in metastatic tumors compared to primary ones." (PMID 38474054, 2024).
neurofibroma (1 paper, 2025). An intraneural or extraneural neoplasm arising from nerve tissues and neural sheaths. "Chen and colleagues reported that the activation of Yap in Schwann cells through knockout of Lats1 and Lats2 drove neurofibroma formation in mice when combined with Nf1 loss, which drives MAPK signaling." (PMID 39804140, 2025).